GFAP (glial fibrillary acidic protein)
Diseases named in the same sentence as GFAP in open-access papers (continued):
Sharing a sentence is not in itself a finding about the gene and the disease.
Autoimmunity (continued). "Glial fibrillary acidic protein (GFAP) immunoglobulin G (IgG) is one of the most common neural autoantibodies in patients with central nervous system (CNS) autoimmunity and a biomarker of a steroid‐responsive subacute meningoencephalomyelitis with or without papillitis." (PMID 39869499, 2025). "MRI changes attributed to GFAP autoimmunity were present in 79%." (PMID 39869499, 2025). "Clinical characteristics of patients with GFAP autoimmunity (N = 56)." (PMID 39869499, 2025). "AQP4-IgG or MOG-IgG from the systemic circulation may enter the CNS through a disrupted blood–brain barrier, potentially initiating primary inflammatory events and damaging astrocytes, while GFAP autoimmunity may occur as a secondary phenomenon." (PMID 40777035, 2025). "NfL levels, reflecting such injury, could possibly have utility as a marker of disease severity in GFAP autoimmunity." (PMID 39869499, 2025). "However, we found an upregulation of MHC class I and granzyme and perforin expressing CD8+ T cells in close apposition to astrocytes, which suggests that cytotoxic T cell-mediated immune reaction is present in GFAP autoimmunity." (PMID 38310187, 2024). "In idiopathic patients the trigger for GFAP autoimmunity remains elusive." (PMID 38310187, 2024). "Alternatively, the lymphocytic and granulomatous phenotypes in human GFAP autoimmunity may reflect different triggers or the influence of specific genetic risk variants." (PMID 38310187, 2024). "The involvement of the peripheral nervous system in GFAP autoimmunity has previously been reported." (PMID 38310187, 2024). "While in subacute/chronic disease stages an overt astrocytic damage was absent, the MHC class I upregulation along with CD8+/perforin+/granzyme A/B+ T cells attached to astrocytes suggest that cytotoxic T cell-mediated immune reaction is present in GFAP autoimmunity." (PMID 38310187, 2024). "The production of GFAP-IgG in patients with GFAP-A may be a result of the virus triggering GFAP autoimmunity or the viral invasion of astrocytes exposing GFAP expression." (PMID 38585352, 2024). "Importantly, GFAP autoimmunity can clinically and pathologically also mimic tuberculous meningoencephalitis or other granulomatous inflammations and should therefore be considered as differential diagnosis." (PMID 38310187, 2024). "Rare causes of autoimmune optic neuropathies, such as glial fibrillary acidic protein (GFAP) and collapsin response-mediator protein 5 (CRMP5) autoimmunity, should also be considered in patients presenting with bilateral painless optic neuropathy associated with optic disc edema." (PMID 38673027, 2024). "Diagnosis of autoimmune GFAP astrocytopathy depends on the presence of GFAP‐IgG in CSF." (PMID 37458208, 2023). "Although coexisting of MOG-IgG and AQP4-IgG were found in a French cohort study, simultaneous involvement of MOG-IgG in the peripheral nervous system was thought to be unusual, and AQP4-IgG was only found in CSF, casting doubt on the existence of an overlap syndrome in GFAP autoimmunity." (PMID 37205100, 2023). "None of our patients had positive anti-GFAP Abs; patients with autoimmunity associated with these Abs have a median age at onset of 44 years and are most commonly women (54%)." (PMID 36969186, 2023). "According to the French cohort, this unique MRI performance may support the hypothesis that GFAP autoimmunity is triggered by infection." (PMID 37205100, 2023). "As some cases are accompanied by tumors, it is suggested that GFAP autoimmunity may be the result of a paraneoplastic immune response initiated by a tumor that generates antibodies that cross-react with neuronal and glial cells." (PMID 36552122, 2022). "In 2016, autoimmune glial fibrillary acidic protein (GFAP) astrocytopathy was first reported as a kind of meningoencephalomyelitis associated with GFAP-IgG, a spectrum of autoimmune inflammatory central nervous system (CNS) disorders, and was subsequently confirmed internationally." (PMID 35065659, 2022).
Autoimmunity (continued). "The presence of GFAP AABs is also described for a novel astroglial autoimmune disorder characterized by CNS inflammation, but these studies so far did not investigate whether the reactivities are up- or down-regulated." (PMID 34943212, 2021). "The results demonstrated the colocalization of DAPI and hCD90 with the expression of BDNF, TGF-β1, GFAP, and interleukin-6 (IL-6) in hAFSCs, indicating that hAFSCs could produce neurotrophic factors and possess anti-autoimmunity and anti-inflammatory effects." (PMID 32572272, 2020). "This classical NMO definition may today segregate into AQP4‐IgG, MOG‐IgG and GFAP‐related autoimmunity or double seronegative NMOSD patients." (PMID 31187587, 2019). "Hence, we retrospectively analyzed the clinical data, biomarkers in CSF, and pathology of patients with astrocyte antibodies to confirm the presence of autoimmune astrocytopathy beyond AQP4 and GFAP autoimmunity and provide new insights into diagnosis and therapy." (PMID 39279053, 2024). "Thus, the different pathologies seen in human GFAP autoimmunity may reflect different stages of lesion development." (PMID 38310187, 2024). "Similarly, tumor cells might express antigens that resemble GFAP, which cross-react with astrocytic GFAP, and induce T-cell mediated autoimmunity, which finally results in neuronal damage." (PMID 39449321, 2024). "Although we could not detect specific GFAP immunoreactivity in the nerve roots in our case, a low level (below immunohistochemical detectability) of GFAP expression in Schwann cells and/or fibroblasts could be involved in triggering neuritis in GFAP autoimmunity." (PMID 38310187, 2024). "However, we point out that these infectious agents might have played a role in triggering GFAP-Abs-mediated autoimmunity, in addition to their own pathogenicity." (PMID 37540278, 2023). "Anti-GFAP antibodies may not be pathogenic, but they do serve as a marker of autoimmunity caused by cytotoxic T cells." (PMID 37205100, 2023). "Therefore, tissues expressing GFAP protein, such as peripheral nerve, autonomic preganglionic fibers, spinal cord, and brain tissue, may be damaged during the onset of autoimmune GFAP astrocytopathy." (PMID 37781407, 2023). "In addition, anti-GFAP or GFAP-BDP autoantibodies are not limited to TBI, Thus caution should be exercised that anti-GFAP might not be a perfect subacute diagnostic of TBI as other factors can contribute to autoimmunity." (PMID 24667434, 2014). "Selective astrocytic damage is prominent in the early phase of GFAP autoimmunity in a canine autopsy case, but mild or absent in subacute and chronic stages in human disease, probably due to the high regeneration potential of astrocytes." (PMID 38310187, 2024). "PNS involvement in GFAP-Abs autoimmunity is heterogeneous but not rare and is mostly represented by acute or subacute cranial nerve injury and/or lower limb radiculopathy." (PMID 37540278, 2023). "Patients with anti-GFAP Abs usually have a high number of cells in the CSF (>50 × 106/L), which contrasts with the paucity of inflammatory response found in the CSF of patients with GAD65 autoimmunity." (PMID 36969186, 2023). "In the case of primary central nervous system lymphoma, GFAP autoimmunity does not always equate to autoimmune GFAP astrocytopathy." (PMID 36552122, 2022). "The pathophysiology of GFAP autoimmunity is not fully elucidated." (PMID 39869499, 2025). "The reason for the lack of obvious astrocytic damage in GFAP autoimmunity (which does not necessarily mean lack of dysfunction) might be a time-dependent factor." (PMID 38310187, 2024). "Firstly, GFAP autoimmunity may not always be a remote effect of the neoplasm but could also happen intrathecally." (PMID 36552122, 2022). "Thus far, the whole picture of GFAP autoimmunity is still not clear." (PMID 36552122, 2022).
frontotemporal dementia (47 papers, 2010 to 2026). Frontotemporal dementia (FTD) comprises a group of neurodegenerative disorders, characterized by progressive changes in behavior, executive dysfunction and language impairment, as a result of degeneration of the medial prefrontal and frontoinsular cortices. "For example, plasma GFAP has demonstrated high effectiveness in distinguishing AD from frontotemporal dementia and progressive supranuclear palsy, suggesting its potential as a CSF-independent biomarker." (PMID 40690136, 2025). "GFAP expression was increased in FTLD-tau (P = 0.0345) with the highest expression in Pick’s disease (P = 0.0019), while ALDH1L1 was unchanged." (PMID 37703311, 2024). "Like the current study, previous studies have found a positive association between age and plasma GFAP levels in patients with AD and frontotemporal dementia (FTD) and higher plasma GFAP levels in females compared to males were observed in patients with AD and TBI." (PMID 37932720, 2023). "CAMK4, a member of the family of calcium/calmodulin-dependent kinases was also found oppositely regulated to GFAP in the neocortex of frontotemporal dementia-like mice with TDP-43 depletion." (PMID 32138778, 2020). "Nevertheless, we validated findings that the GFAP/NfL ratio may discriminate frontotemporal lobar degeneration with tau versus TDP-43 pathology." (PMID 40075459, 2025). "Beyond AD, a rise in GFAP levels in frontotemporal dementia may indicate the late presymptomatic stage, as well as the severity of the disease [26,27▪]." (PMID 36607770, 2023). "Although the overexpression of astrocyte-specific proteins, such as the glial fibrillary acidic protein (GFAP), was detected also in patients with frontotemporal lobar degeneration with MAPT mutation(s) (FTLD-MAPT), the EWCE analysis pointed towards functionally defective oligodendrocytes." (PMID 37296571, 2023). "Additionally, astrocytosis is mainly observed in younger frontotemporal dementia patients, and this is supportive for our findings regarding the correlation between kif21b and GFAP only in the young AD patients." (PMID 25274010, 2014). "In the present study, we compared plasma GFAP levels in the most extensive ALS cohort examined to date with those of patients with frontotemporal dementia (FTD) and neurological controls." (PMID 37762278, 2023). "Blood GFAP levels increase with aging and are further elevated in females, MCI, AD, Parkinson's disease, and frontotemporal dementia (FTD) but are not affected by the APOE ε4 allele." (PMID 40145342, 2025). "Nonetheless, this is of particular interest because both NfL and GFAP were shown to be increased also in non-AD neurodegenerative disorders such as frontotemporal dementia." (PMID 38755703, 2024). "Moreover, astrogliosis and GFAP upregulation is not specific for AD dementia and any neurological injury from fronto-temporal dementia or vascular dementia can evoke astrocytic response and GFAP upregulation." (PMID 41002922, 2025). "However, increased GFAP levels have also been found in patients with PD, APD, frontotemporal dementia (FTD), multiple sclerosis, prion diseases, and ALS." (PMID 41206819, 2025).
Hyperglycemia (41 papers, 2015 to 2025). An increased concentration of glucose in the blood. "Hyperglycemia-caused retinal damage drives Müller cells to become active, characterized by the upregulation of GFAP expression." (PMID 39706273, 2024). "Interestingly, hyperglycemia also caused the stress condition of astrocytes and Müller cells, which was suggested by the increased expression of retinal GFAP in DR rats and these findings were in agreement with previous studies." (PMID 31396288, 2019). "In addition, ranirestat, an inhibitor of the enzyme aldose reductase, which has an early role in the development of DR, exerts neuroprotective effects by reducing GFAP accumulation and preventing hyperglycemia-associated structural damage of the retina." (PMID 29464181, 2017). "Studies conducted using rodent models have revealed GFAP protein levels to be reduced following CUMS exposure, whereas hyperglycemia has been associated with elevated GFAP expression." (PMID 41462586, 2025). "Previous studies have also reported a loss of GFAP-positive astrocytes in other brain regions of T2DM subjects, although the mechanisms underlying hyperglycemia-induced astrocytic dysfunction require further investigation." (PMID 41023469, 2025). "This is corroborated by studies that showed that reactive gliosis can happen in response to hyperglycemia characterized by an upregulated level of GFAP, a marker of glial cell activation." (PMID 40341376, 2025). "After 4 weeks of hyperglycemia, retinal tissue displays a decrease in tyrosine hydroxylase (TH) levels, but an increase in the levels of GFAP, NF-κB and IKK, consistent with inflammation." (PMID 39056672, 2024). "Müller cells are predominant glial cells in the retinal tissues, and reactive gliosis can happen in response to hyperglycemia featured by an upregulated level of GFAP (a glial activation marker)." (PMID 38282961, 2024). "This hyperglycemia-induced GFAP expression persisted after glucose normalization, but it was inhibited in HGM mice by K9-C-peptide." (PMID 36782199, 2023). "The upregulation of GFAP expression and the elevated rate of apoptosis in the outer nuclear layer were observed in the diabetic retina after 27 weeks of hyperglycaemia." (PMID 36829539, 2023). "In contrast, GFAP expression was found to decrease in rat astrocytes with hyperglycemia, and GFAP expression increased after correction of hyperglycemia." (PMID 38026658, 2023). "We previously reported a strong upregulation of RelA and GFAP in retina after 4-weeks of hyperglycemia." (PMID 38983568, 2022). "They respond to hyperglycemia by increasing the synthesis of glial fibrillary acid protein (GFAP) and vimentin and by producing inflammatory and angiogenic cytokines, such as hypoxia-inducible factor (HIF)-1." (PMID 36613769, 2022). "Experimental studies have shown overexpression of GFAP (termed astrogliosis) in response to both hyperglycemia and type 1 diabetes." (PMID 31481433, 2019). "Neuroinflammation in the mouse hippocampus was substantially increased by hyperglycemia as determined by GFAP (hypertrophic astrocytes, P < 0.001) and Iba1 (activated microglia, P < 0.001) staining." (PMID 30426182, 2019). "The number of GFAP-positive cells in the hippocampus was significantly increased in diabetic rats at 5 and 9 weeks of hyperglycemia (P < 0.001)." (PMID 30692917, 2018). "Upregulation of GFAP occurs in response to hyperglycemia as well as other retinal insults, including light damage, photoreceptor degeneration and retinal detachment." (PMID 30158110, 2018). "In normoglycemia, GFAP expression is restricted to astrocytes at the retinal surface, whilst in hyperglycaemia and other situations of retinal stress, Müller cells exhibit GFAP along the length of their cell processes." (PMID 26222724, 2015). "Our findings suggest that the effect of CUMS may override that of hyperglycemia, resulting in an overall decrease in GFAP protein content." (PMID 41462586, 2025).
Hyperglycemia (continued). "However, astrocyte markers, including CD44, KCNJ10, TGFBR2, GFAP, and S100β, were upregulated under hyperglycaemia, as shown by both NGS transcriptomic analysis and immunostaining." (PMID 41419458, 2025). "Despite more frequent hypoglycemia in T1DM, both persons with T1DM and T2DM commonly experience hyperglycemia, which may explain our findings of lower GFAP-expressing astrocytes in both groups." (PMID 41023469, 2025). "GFAP upregulation in glial cells and reactive gliosis occurred at 4–5 weeks of hyperglycaemia." (PMID 36829539, 2023). "Hyperglycemia induces the stress protein marker GFAP expression in MC." (PMID 35075205, 2022). "Increased GFAP indicates reactive gliosis and might result from hyperglycemia, oxidative stress, hypoxia, or inflammation in diabetic retinas." (PMID 35334819, 2022). "In conclusion, our findings from in vivo and in vitro experiments showed that the mTOR inhibitor, rapamycin, blocks the up-regulation of VEGF and GFAP in the diabetic rat retina and also inhibits the hyperglycemia-induced increase in ROS in cultured Müller cells and HERMCs." (PMID 33479328, 2021). "This difference could be attributed to the timeline of GFAP upregulation that commences as early as 3 weeks after hyperglycemia and increases over time." (PMID 33498409, 2021). "Furthermore, among the effects of hyperglycemia seen in glial cells, It has been shown that GFAP immunoreactivity increases in the hippocampus of streptozotocin treated mice." (PMID 32019062, 2020). "Retinal studies with streptozotocin-induced hyperglycemia in rodents have suggested that hyperplasia of Müller cells (retinal analogue of astrocytes) could lead to an increase in GFAP." (PMID 31481433, 2019). "In diabetic patients the microcirculation, impaired by hyperglycemia, may be further damaged by the upregulation of GFAP with the subsequent gliosis and the ILM peeling with Müller cells collapse." (PMID 29738569, 2018). "We conclude that hyperglycemia does not cause major changes in astrocytic GFAP expression in the mouse brain." (PMID 30498224, 2018). "In addition, activation of GFAP and GS was found in Müller cells exposed to hyperglycemia." (PMID 39150511, 2025). "Reactive gliosis represents the response of Müller cells to hyperglycemia, a process characterized by a specific pathophysiological mechanism: hypertrophy, cellular proliferation, and increased intermediate filament proteins nestin, vimentin and glial fibrillary acidic protein (GFAP)." (PMID 28238189, 2017). "Our data similarly showed upregulation of GFAP and CD44, indicating reactive gliosis in response to hyperglycaemia." (PMID 41419458, 2025). "Our results also revealed that hyperglycemia-induced neuroinflammation resulted in decreased NeuN and BDNF expression and abnormally increased GFAP expression in the HFD/STZ group." (PMID 38952685, 2024). "After 4 weeks of hyperglycemia, there are also reductions in photopic ERG responses, decreases in cognition, and increases in inflammatory markers (Rel-A/NF-κB, IKK, GFAP) in both the retina and the brain." (PMID 39056672, 2024). "In this study we show that rapamycin effectively attenuates the hyperglycemia-induced overexpression of VEGF and GFAP in the rat retina." (PMID 33479328, 2021). "Therefore, we examined changes in AKT, GSK3β, NeuN, BDNF, and GFAP expression in a rat model, and our data showed that AKT and downstream GSK3β expression was reduced in the brains of rats with HFD/STZ-induced hyperglycemia." (PMID 38952685, 2024). "GFAP expression was increased at 4 weeks of hyperglycemia but decreased at 8 weeks, and did not increase with insulin treatment." (PMID 36552776, 2022). "At our 8-week time point, the increase in GFAP levels is no longer significant in brain or retina, despite continued hyperglycemia." (PMID 38983568, 2022). "In addition, the up-regulated expression of glia marker GFAP was observed, indicating that circVPS13A attenuated EGC damage under hyperglycemia." (PMID 35880571, 2022).